LRP1 (LDL receptor related protein 1)
Diseases named in the same sentence as LRP1 in open-access papers (continued):
Sharing a sentence is not in itself a finding about the gene and the disease.
cancer (continued). "Secreted Hsp90 plays a powerful role in cancer cell invasiveness through both binding to the surface receptors such as LRP1/CD91, and interacting with matrix metalloprotease 2 on the cell surface to mediate invasiveness, EMT, and a TIC phenotype." (PMID 31514477, 2019). "LRP1 has recently been identified as a hub within a biomarker network for multi-cancer clinical outcome prediction." (PMID 29507659, 2018). "LRP1 is a large, multi-ligand signaling receptor which has been discussed in numerous contexts, ranging from cancer to oligodendritic cholesterol homeostasis to ECM remodeling." (PMID 30154697, 2018). "LRP1 (low-density lipoprotein receptor-related protein 1), a multifunctional endocytic receptor, has recently been identified as a hub within a biomarker network for multi-cancer clinical outcome prediction." (PMID 29507659, 2018). "More recently, an elegant network-based exploratory study found LRP-1 as being highly connected to a multi-cancer gene expression biomarker, which appears to be strongly predictive of clinical outcome in 12 types of cancers." (PMID 29108253, 2017). "Our findings provide new mechanistic insights that help to improve the understanding of LRP-1 contribution in cancer cells." (PMID 29108253, 2017). "From our results, we believe that it is likely that LRP-1 plays a role in such cancer-related processes by directing and maintaining β1-integrin to the endosomal traffic." (PMID 29108253, 2017). "Here, we identified that YAP has a positive impact on the expression of LRP1, which also plays critical roles in cancer." (PMID 29138479, 2017). "Nevertheless, the relatively poor knowledge of LRP-1 transmembrane interactome impedes our thorough understanding of the way it controls cell-matrix interaction dynamics and contributes to malignant disease progression." (PMID 29108253, 2017). "LRP1 gene silencing in cancer cells was indeed found to accelerate cell attachment, provoke major actin-cytoskeleton rearrangements and induce the accumulation of abundant talin-containing focal adhesion complexes." (PMID 29108253, 2017). "Other mechanisms have also been shown to contribute to LRP1-mediated MMP-dependent cancer cell invasion and migration." (PMID 26738504, 2016). "An increasing number of studies have confirmed that LRP1 promotes cancer cell invasion and migration." (PMID 26738504, 2016). "Another mechanism by which LRP1 promotes cancer cell invasion is via activation of ERK and inhibition of JNK signaling pathways, which are two major MAPK pathways." (PMID 26738504, 2016). "Accumulating studies reported that LRP1 in monocytes and macrophages plays a critical role in cancer progression by acting as a regulator of inflammation." (PMID 26738504, 2016). "LRP1 expression levels are often downregulated in cancer and some studies consider low LRP1 levels a poor prognostic factor." (PMID 26617523, 2015). "All in all, given its role in cancer cell invasiveness, LRP-1 represents a therapeutic target against metastasis whose inhibition will most probably constitute a selective pharmacological approach." (PMID 25629807, 2015). "The membrane protein low-density lipoprotein receptor related-protein 1 (LRP1) has been attributed a role in cancer." (PMID 26617523, 2015). "Although LRP-1 has been shown to be up-regulated in various cancers, its role and signaling in carcinogenesis and progression is context-dependent." (PMID 25514242, 2014). "Despite a strong stimulation of pericellular MMP-2 and uPA proteolytic activities, carcinoma cell invasion decreased by LRP-1 silencing." (PMID 23936774, 2013). "PAI-1 inhibited the motility of vascular smooth-muscle cells, human amnion WISH cells, and carcinoma cells via interaction with vitronectin, and vitronectin blocked the LRP1/PAI-1 pathway." (PMID 22747686, 2012). "Under hypoxic conditions, both cancer cell lines increased LRP1 expression by about 110% and 70%, respectively." (PMID 22027709, 2011).
cancer (continued). "The experiments here examined the role of LRP1 in the subsequent endocytosis of drug into cancer cells." (PMID 22027709, 2011). "In two other cancer cell lines (bone and liver), we found that hypoxia similarly upregulated expression of LRP1." (PMID 22027709, 2011). "Although the precise mechanisms for LRP1 in malignancy remain controversial, accumulating evidence of its role in cancer progression encourage further studies on the interplay between an aggressive phenotype and uptake of ANG1005 and other EPiC agents." (PMID 22027709, 2011). "Extracellular Hsp90 protein (eHsp90) potentiates cancer cell motility and invasion through a poorly understood mechanism involving ligand mediated function with its cognate receptor LRP1." (PMID 21408136, 2011). "Our data demonstrated that LRP-1-mediated regulation of MAPK signaling triggers FA dynamics of cancer cells, supporting cell invasion." (PMID 20644732, 2010). "Recent studies have reported a positive contribution of LRP-1 to migration and invasion events of various cell types, including malignant tumor cells." (PMID 20644732, 2010). "The lack of mechanistic insights into the intracellular signaling networks downstream of LRP-1 has prevented the understanding of its contribution towards cancer." (PMID 20644732, 2010). "The number of LRP-1-expressing cancer cells positive for talin-rich adhesion complexes was increased by about 1.4-fold under ERK inhibition (U0126 and dn-MEK) and by 1.7-fold under JNK activation (MKK-7/JNK-1)." (PMID 20644732, 2010). "The low-density lipoprotein receptor-related protein-1 (LRP-1) is an endocytic receptor mediating the clearance of various extracellular molecules involved in the dissemination of cancer cells." (PMID 20644732, 2010). "A growing number of evidence strengthened the putative role of LRP-1 in crucial events during cancer progression." (PMID 20644732, 2010). "Future investigation should focus on identifying MAPK-modulating sequences in LRP-1-ICD to open therapeutic perspectives in the prevention of cancer dissemination." (PMID 20644732, 2010). "We recently demonstrated that LRP-1 contributes to carcinoma cell invasion by subtly controlling adhesive complex turnover." (PMID 20644732, 2010). "We first demonstrated that LRP-1 expression in carcinoma cells triggers the serum-mediated activation of ERK and is responsible for the constitutive inhibition of JNK." (PMID 20644732, 2010). "In order to explore the function of adipocytic LRP1, we first investigated the level of LRP1 protein expression in preadipocytes relative to fibroblasts and epithelial cancer cells." (PMID 19823686, 2009). "Consequently, the interaction of LRP1 with integrins emerges as a potential candidate target for preventing cancer invasion." (PMID 38950861, 2024). "Consequently, pan-cancer considerations have been extended to include LRP1 as a prospective theragnostic target." (PMID 39063239, 2024). "Therefore, we investigated the correlation between LRP1 expression and immune infiltration in various cancers using the TIMER database." (PMID 39063239, 2024). "In GBM, silencing of LRP1 was associated with a decreased level of phosphorylated ERK‐1/2 and increased levels of phosphorylated JNK‐1/2/3, suggesting a potential pivotal role of LRP1 in regulating intracellular signal transduction involved in cancer progression." (PMID 39276062, 2024). "Other studies established that LRP-1 may constitute a strong predictive marker of clinical outcome in 12 types of cancers." (PMID 37768946, 2023). "The mannosylated lactoferrin nanoparticles (Man‐LF‐SHK/JQ1 NPs) were prepared for delivering shikonin (a naphthoquinone pigment isolated from the traditional Chinese herb Zicao) and JQ1 (a PD‐1 blockage agent) to cancer cells and TAMs via mannose receptor (MR) and LRP1." (PMID 36599655, 2023). "It is also known that tPA activates invasion of cancer cells via direct binding to LRP1." (PMID 36839884, 2023).
cancer (continued). "Moreover, the clearance of cancer cells by macrophages was also suppressed following psychological stress via disturbing the balance of the “eat me” signal receptor LRP1 and “don’t eat me” signal SIRPα on macrophages." (PMID 37210553, 2023). "Numerous studies have suggested a role for LRP1 in the regulation of cell invasion and migration in several cancers, and it may suppress CRC progression." (PMID 36973740, 2023). "LRP-1 plays a vital role in maintaining the TME and regulating cancer invasion due to its association with intracellular signaling and endocytosis of different types of cancer." (PMID 36980778, 2023). "LRP1 plays important roles in regulating lipid homeostasis, glucose metabolism, and inflammation, and has been shown to be involved in extracellular matrix remodeling and cancer progression." (PMID 37153545, 2023). "Studies have indicated the role of LRP-1 in cancer progression." (PMID 36703790, 2022). "Based on the findings presented in this report, we predict that therapeutic strategies, which augment PSAP activity and inhibit PRSS2 binding to LRP1 could hold tremendous therapeutic potential for cancer patients." (PMID 36575174, 2022). "Patients with mutations in LRP1, ACVR2A, and SETBP1 tend to have a family history of cancer." (PMID 35814400, 2022). "This LRP-1 dual mode of control of calpain activity fine-tunes carcinoma cell spreading." (PMID 36052226, 2022). "Similarly, several other receptors, such as gonadotropin-releasing hormone (GnRH), LDL receptor-related protein 1 (LRP1), somatostatin subtype-2, and transferrin, are being targeted for delivery of chemotherapeutics to the cancer site." (PMID 34063098, 2021). "Moreover, quantitative real-time PCR suggested that the expression levels of MAOB and LRP1 were downregulated in cancer tissues compared with paracarcinoma tissues, and the expression of FASN was upregulated." (PMID 34819038, 2021). "LRP-1-dependent endocytosis and signaling-related events have been shown to play critical roles in severe pathologies including both Parkinson’s and Alzheimer’s diseases, metabolism dysfunction and cancer." (PMID 32582700, 2020). "On the other hand, LRP1 may promote cancer progression by serving as a receptor for the growth factor, midkine, by signaling through ERK1/2 to induce expression of MMPs, and by facilitating survival of micro-metastases." (PMID 29088295, 2017). "In nine of ten cancers, LRP1 was the most abundantly expressed LRP at the mRNA level." (PMID 29088295, 2017). "In addition, LRP-1 interaction with membrane-bound calreticulin was shown to stimulate focal adhesion reorganization in non-cancer cells." (PMID 29108253, 2017). "It was therefore proposed that the ability of LRP-1 to mediate endocytosis of transmembrane proteins may explain its role in coordinating the adhesion-deadhesion balance of cancer cells." (PMID 29108253, 2017). "The CVs for LRP1 mRNA expression in individual cancers ranged from 0.52–0.79." (PMID 29088295, 2017). "The relationship between LRP1 and a variety of cancers has been reported." (PMID 26738504, 2016). "Hence, in this review, we focus on recent translational studies that describe the roles of LRP1 in cancer cell proliferation, apoptosis, migration, invasion, and angiogenesis." (PMID 26738504, 2016). "Consequently, LRP1 is suggested to be involved in two major cell processes: endocytosis and modulation of signaling pathways, which play diverse biological roles in cancer cells." (PMID 26738504, 2016). "Therefore, it is likely that, in addition to clearing the extracellular environment, LRP1-mediated endocytosis of ligands contributes to the delivery of cancer-promoting signals in cells." (PMID 26738504, 2016). "Moreover, LRP1 can be regulated via methylation of LRP1 CpG islands as well as miR-205, which further complicates the role of LRP1 in cancer cells." (PMID 26738504, 2016).
cancer (continued). "Caspase-3 is a key enzyme in cell apoptosis, suggesting that LRP1 may also inhibit cancer cell apoptosis by regulating the activation of Caspase-3." (PMID 26738504, 2016). "Future large scale studies on patient samples could provide more insights and demonstrate the true relevance of LRP1 in diagnosis and prognosis of cancer." (PMID 26617523, 2015). "It should be noted, however, that under normoxia cell culture conditions cancer cell lines in vitro might show a reduction in LRP1 expression compared to hypoxic conditions." (PMID 26617523, 2015). "Besides this, probably far from complete, overview of LRP1-related ECM modifying processes, LRP1 also forms co-receptor complexes at the cell surface with receptors involved in cancer-related pathways." (PMID 26617523, 2015). "Via a diverse array of interactions LRP1 modulates various pathways involved in cancer." (PMID 26617523, 2015). "These should answer the question whether LRP1 could be a valuable target for diagnosis, prognosis and therapeutics in cancer as well as other diseases." (PMID 26617523, 2015). "This further illustrates the involvement and possible prognostic value of LRP1 in various cancers." (PMID 26617523, 2015). "Nonetheless, more recent work supports a reduction in LRP1 expression in cancer." (PMID 26617523, 2015). "Since LRP1 mutations have not been reported in cancers, we predict that these mutations exert a similar effect as their gene amplification events." (PMID 26317392, 2015). "The weak expression level of LRP-1 observed in high grade human cancer cells and tissues seemed to support such a hypothesis." (PMID 20644732, 2010). "Considering the impact of LRP-1 silencing on the adhesive and morphological properties of carcinoma cells, we investigated whether the LRP-1-mediated control of MAPK is necessary for FA turn-over." (PMID 20644732, 2010). "Next, we used the selective JNK inhibitor SP600125 and a dominant-negative mutant of JNK to recover JNK inhibition in LRP-1-deficient carcinomas." (PMID 20644732, 2010). "We therefore investigated whether the LRP-1-dependent activation of ERK could contribute to carcinoma cell invasion." (PMID 20644732, 2010). "However, Src inhibition did not affect the invasive capacities of both shCTRL and shLRP-1 cells, thereby excluding Src kinase contribution to LRP-1-mediated ERK activation during carcinoma cell invasion." (PMID 20644732, 2010). "Importantly, though, numerous studies propose a dual role of LRP1 in cancer." (PMID 37020553, 2023). "Indeed, LRP1 expression is often deregulated in human cancers." (PMID 33544155, 2021). "However, evaluation of provisional databases in the Cancer Genome Atlas (TCGA) showed that in nine of ten cancers studied, a statistically significant correlation between LRP1 mRNA expression and patient survival was observed only in bladder urothelial carcinomas." (PMID 34281263, 2021). "Lrp1 may modulates cancer progression, and Tubb4b may be related to human cancer." (PMID 32256870, 2020). "That is why strategies targeting LRP-1 could affect the capability of cancer cells to invade." (PMID 33233645, 2020). "Therefore, it is not surprising that changes in Lrp1 expression and phosphorylation status are associated with neurodegenerative and cardiovascular diseases and cancer." (PMID 30931303, 2019). "In addition, methylation of LRP1 CpG islands may represent a novel diagnostic marker for ESCC and other cancers." (PMID 26738504, 2016). "However, recent results suggest that LRP-1 may facilitate the development and growth of cancer metastases in vivo, but the precise contribution of the receptor during cancer progression remains to be elucidated." (PMID 20644732, 2010). "However, the phosphorylation levels of Akt and p38 MAPK did not change significantly in LRP-1-deficient carcinomas." (PMID 20644732, 2010). "Likewise, we examined to what extent LRP-1-mediated inhibition of the JNK pathway could support carcinoma cell invasion." (PMID 20644732, 2010).
cancer (continued). "Through LRP1-mediated activation of the AKT/ERK1/2 pathway, PAI-1 promotes the migration and invasion of both cancer cells and macrophages, correlating with poor prognosis and identifying the PAI-1/LRP1 axis as a promising therapeutic target." (PMID 41601623, 2026). "eHsp90 interacts with cell-surface receptors, including low-density lipoprotein receptor-related protein-1 (LRP1) and toll-like receptors (TLR2 and TLR4), thereby promoting cancer cell proliferation, migration, and invasion." (PMID 41226319, 2025). "Validation in TCGA datasets revealed significant correlations between LRP1, FASN, SIRT6, and clinical outcomes in BC patients, suggesting their potential as cancer biomarkers." (PMID 39071712, 2024). "The dysregulated expression observed in various cancers positions SIRT6, LRP1, and FASN as potential candidates for cancer biomarkers." (PMID 39071712, 2024). "Validation in TCGA datasets highlighted the prognostic significance of LRP1, FASN, and SIRT6, suggesting their potential as cancer biomarkers." (PMID 39071712, 2024). "Our TIMER-based investigation found a significant correlation between LRP1 levels and various immune cell types, including B cells, CD4+ and CD8+ T cells, neutrophils, macrophages, and dendritic cells across multiple cancer types." (PMID 39063239, 2024). "The secretion of the HSP90 cochaperone protein Morgana induces cancer cell migration by activating TLR2, TLR4, and LRP1." (PMID 38052785, 2023). "Silencing TM expression enhanced the anti-cancer effect of curcumin, and in addition to that, TM expression levels influenced the modulation of ABCC1, LRP1, and MDR1 drug-resistant-related genes." (PMID 37239055, 2023). "The top outgoing signaling from epithelial cancer cells to CAFs (communication probability > 0.10) showed interactions between MIF (cancer cells) and CD74 + CD44 (CAFs) or MDK (cancer cells) and NCL/SDC2/LRP1 (CAFs)." (PMID 36352420, 2022). "Several upregulated genes (LRP1, SERPINA1, HRG, ILK, CAV1, and LAMA4) identified in our study are involved in GEM resistance in human cancer 23-28." (PMID 35281857, 2022). "TSP-1 is known to bind integrins, Low Density Lipoprotein Receptor Related Protein-1 (LRP1), EGFR, TGF-beta, urokinase-type Plasminogen Activator (uPA), and VEGF-A, all of which are expressed on, or bind to, cancer cells (GEMICCL)." (PMID 36546919, 2022). "In pancreatic cancer cells, TAM express and secrete eHSP90α that binds to LRP1 and activates the Janus kinase (JAK) 2-STAT3 pathway, leading to cancer progression." (PMID 33544155, 2021). "eHSP90 binding to LRP1 activates ERK, AKT, and NF-κB pathways and induces ephrin type-A receptor 2 (EPHA2) recruitment and activation, promoting lamellipodia formation and cancer cell motility and invasion." (PMID 34722515, 2021). "Low-density lipoprotein receptor-related protein 1 (LRP1) is a common receptor for many extracellular chaperones, both in normal and cancer cells where its expression is often upregulated." (PMID 34360868, 2021). "It has been reported that the eHsp90α-LRP1 interaction gives rise to a series of promotility signal cascades, such as AKT and ERK activation to promote cell motility during wound healing and cancer progression." (PMID 34299365, 2021). "LRP-1 is considered as a key integrator of signals from the ECM and a multifunctional regulator of cancer-related events." (PMID 32582700, 2020). "The resulting heatmap showed that in the majority of malignancies, TILs were significantly correlated with multiple representative ICD mediators, such as CALR, LRP1, ANXA1, FPR1, TLR3, IFNAR1, PANX1, and P2RX7." (PMID 33299118, 2020).